RN7SL268P (RNA, 7SL, cytoplasmic 268, pseudogene)
Gene: Miscellaneous RNA gene on chromosome 22 (23,879,493 to 23,879,790, reverse strand). Ensembl gene ENSG00000244425.
Homologues: Orthologues: chimpanzee Metazoa_SRP (98% identical). Paralogues in human: RN7SL156P (77% identical), RN7SL33P (77% identical), RN7SL234P (75% identical), RN7SL1 (74% identical), RN7SL2 (74% identical), RN7SL220P (73% identical), RN7SL7P (73% identical), RN7SL650P (73% identical), RN7SL3 (73% identical), RN7SL543P (73% identical), RN7SL333P (72% identical), RN7SL630P (72% identical), and 702 more.